EGFR (epidermal growth factor receptor)
Diseases named in the same sentence as EGFR in open-access papers (continued):
Sharing a sentence is not in itself a finding about the gene and the disease.
tumor (continued). "This study is the first to compare PANAMutyper and cobas v2, two popular commercial EGFR mutation tests in Korea, for testing in both tumor and plasma samples from NSCLC patients." (PMID 32224854, 2020). "In HNC, EGFR is a key receptor that is known to be involved in tumor progression and metastasis and its expression associated with poor prognosis." (PMID 32028632, 2020). "In particular, circulating cell-free tumor DNA (cftDNA) in plasma has emerged as a specific and sensitive blood-based biomarker for the detection of EGFR mutations." (PMID 33297595, 2020). "They found that plasma EGFR T790M detection was associated with a larger median baseline tumor size and presence of extrathoracic disease." (PMID 36046486, 2020). "The NIC values of the EGFR mutated tumours were significantly higher than those of the EGFR wild-type tumours in both the AP (0.18 ± 0.08 versus 0.13 ± 0.06, P = 0.032) and VP (0.47 ± 0.14 versus 0.37 ± 0.07, P < 0.001)." (PMID 32103127, 2020). "An association between a specific molecular trait of the tumor and immune-cold microenvironment, that predisposes to resistance to immunotherapy, exists in EGFR mutant tumors." (PMID 33276569, 2020). "The heterogeneity of tumor cells causes EGFR to participate in different manifestations of cells in response to EF stimulation." (PMID 32210363, 2020). "The incidence of tumor associated EGFR mutation and anaplastic lymphoma kinase (ALK) rearrangement varies from 10% (in the USA) to 35% (in East Asia) and 5–7%, respectively, in patients with NSCLC." (PMID 32770960, 2020). "It has been proposed that a drop in the expression of Beclin-1 in GBM tissue enhances EGFR overexpression; therefore, higher EGFR levels and decreased levels of the protein Beclin-1 have been associated with tumor progression and a poorer prognosis." (PMID 32707662, 2020). "It has been reported that overexpression of EGFR and AurkA in tumor tissues is a risk factor associated with poor disease-free survival and therapy resistance." (PMID 35047986, 2020). "What potential impact of EGFR mutated cancer cells expressing PD-L1 in tumor cell population remains be illuminated." (PMID 32093629, 2020). "In this study, we demonstrated 100% concordance in the detection of EGFR mutations in tumor tissue and CTCs isolated from a total of 15 samples collected from 13 patients, including two cases of the emergence of the T790M mutation." (PMID 32373206, 2020). "In this study, we also demonstrated that the majority of EGFR oncogenic mutations were encapsulated within the exosomes in cell culture media of tumor cell lines and in biofluids from NSCLC patients." (PMID 32722209, 2020). "Resistance to targeted therapies such as anti-EGFR mAbs emerges through the selection of tumor clones harboring an innate mutation of resistance." (PMID 32825275, 2020). "This explanation is further supported by the overwhelming recurrence in lung parenchyma and pleura observed in the EGFR-mutated group, as these sites would be most affected by increased tumor cell burden in pulmonary veins." (PMID 32523650, 2020). "We evaluated two EGFR mutation tests, cobas v2 and PANAMutyper, for detection of EGFR activating mutations Ex19del, L858R, and T790M in tumor tissue and plasma from 244 non-small cell lung cancer (NSCLC) patients." (PMID 32224854, 2020). "The tumor EGFR mutation status was determined by genotyping of the plasma and BWF samples using droplet digital PCR (ddPCR)." (PMID 32517757, 2020).
tumor (continued). "In particular, EGFR overexpression is associated with decreased survival rates and increased tumor size." (PMID 31996230, 2020). "Epidermal growth factor receptor deletion mutant variant III (EGFRvIII) is a tumor-specific antigen expressed in GB and its expression is often associated with survival, invasion, angiogenesis and resistance to radio- and chemotherapy." (PMID 33101285, 2020). "In particular, in GBM, EGFR is amplified in 40%, overexpressed in 60% and mutated or deleted in 24–67% of primary tumours." (PMID 32823532, 2020). "Numerous human malignancies displayed EGFR expression, which is linked to a neoplasm progression and tumor grades along with cancer poor prognosis." (PMID 33680380, 2020). "Transient activation (or blocking) of EGFR is associated with tumor cell proliferation, whereas sustained activation can lead to cell differentiation." (PMID 33028895, 2020). "The most frequent EGFR mutations (sensitizing activating mutations) are associated with tumor sensitivity to EGFR tyrosine kinase inhibitors (gefitinib, erlotinib, and afatinib)." (PMID 31901171, 2020). "Analysis of circulating cell-free tumor DNA (cftDNA) has emerged as a specific and sensitive blood-based approach to detect epidermal growth factor receptor (EGFR) mutations in non-small cell lung cancer (NSCLC) patients." (PMID 33297595, 2020). "We identified 250 eligible patients whose tumor samples were available and previously genotyped for EGFR mutations by PNAclamp, and 185 of those patients had plasma samples available." (PMID 33266057, 2020). "The fact that cancers with EGFR mutation partially expressed PD-L1 protein suggests that a tumor mass seems to exist as if intercoursed subpopulations of cancer cells present with different biological behavior, both in PD-L1 expression and EGFR mutation." (PMID 32093629, 2020). "Tumour genotyping revealed somatic EGFR co-mutations in 94% of probands: 6 exon 19 del, 12 L858R, 6 G719X, 1 exon 19 del and G719R, 1 L861Q, 2 H773R and 1 V774M." (PMID 32104210, 2020). "As outlined in Section 2, EGFR mutations were reported as genetic drivers of PD-L1 expression thereby contributing to tumor immune escape." (PMID 32486375, 2020). "EGFR tyrosine kinase inhibitors (EGFR-TKIs) have higher anti-tumor activities in NSCLC patients who harbor an activating EGFR mutation." (PMID 32179761, 2020). "A possible method is to analyze the plasma for driver mutations identified in the tumor, e.g., epidermal growth factor receptor (EGFR) exon 21 p.L858R or Kirsten rat sarcoma (KRAS) exon 2 p.G12D." (PMID 32117779, 2020). "Previously it has been shown that mutations in EGFR pathway components resulted in a similar tumor-like germ cell phenotype." (PMID 32111103, 2020). "Patients with stage IB to IIIA after radical surgery will get molecular analysis, and patients whose tumor harbors an EGFR mutation will enter the EGFR mutation substudy." (PMID 32878298, 2020). "75% of these tumor samples showed ≥1 (likely) pathogenic mutation, including targetable mutations (e.g. EGFR, BRAF, MET, ERBB2, KIT, PDGFRA)." (PMID 32264863, 2020). "In NSCLC, mutations of the epidermal growth factor receptor (EGFR) play an important role in the growth and progression of tumour cells." (PMID 31541309, 2020). "We found that p110β, a key activator of the AKT pathway in PTEN‐deficient tumor cells, co‐immunoprecipitated with endogenous EGFR in two different TNBC cell lines (Figs EV3D and 3H–I)." (PMID 32672423, 2020).
tumor (continued). "We have not performed CSF cfDNA mutation detection by NGS in P2 or P6, but the EGFR mutation in P6 tumor was detected by other method in 2012." (PMID 33377642, 2020). "EGFR is overexpressed or mutated in most tumours, resulting in dysregulation of the signal transduction pathway, uncontrolled cell growth, and inhibition of cancer cell apoptosis." (PMID 32728182, 2020). "Somatic mutation detection efficiency, for exons 19 & 21 of the EGFR gene, was compared in 116 formalin fixed paraffin embedded tumor tissues, after screening 275 tumor tissues by Sanger sequencing." (PMID 32962681, 2020). "We discuss the development and testing of a bispecific LTT targeting EGFR and urokinase-type plasminogen activator receptor (uPAR) as two attractive targets implicated in tumor growth and in the regulation of the tumor microvasculature in solid tumors." (PMID 32630411, 2020). "Activation of the EGFR signaling pathway in cancer cells is associated with increased tumor growth, angiogenesis, and cell proliferation." (PMID 32111094, 2020). "Ten to twenty percent of patients with EGFR-mutated tumours acquire EGFR-TKI resistance through MET amplification, and the therapeutic implications of this are being explored." (PMID 31598903, 2020). "According to the positive correlation between IPO13 upregulation and EGFR mutations in NSCLC tumor, GSEA was performed on the gene ontology (GO) and KEGG databases." (PMID 33082305, 2020). "Treatment with navitoclax plus ABT-414 caused a significant reduction in tumor growth in five of seven PDXs and significant tumor regression in the highest EGFR-expressing PDX." (PMID 33256808, 2020). "In this study, apoptosis was stained in tumor tissues and the results showed that EGFR mutation samples had a higher apoptosis ratio of tumor infiltrating cells than wild‐type." (PMID 32500560, 2020). "At this time, other than HER2 amplification, two novel mutation, EGFR-ZNF880 fusion and EGFR E114K mutations, were identified in circulating tumor DNA by NGS." (PMID 33371069, 2020). "The next important step for this tracer is to assess its capacity to predict the tumour EGFR mutational status, as this is a strong predictor for response to EGFR-directed TKI therapy, such as afatinib." (PMID 32804306, 2020). "Inclusion of newer promising biomarkers such as type of EGFR mutations, PD-L1 expression and tumor mutational burden (TMB) in combination with body composition seems plausible." (PMID 33194687, 2020). "This particular CART-cell therapy was found to be safe, the infused product reached tumor site in the brain, and also found to assert anti-tumor activity by decreasing EGFR variant III expression." (PMID 32765498, 2020). "After two years of treatment with EGFR-tyrosine kinase inhibitor (TKI), her tumor developed an EGFR T790M (exon 20) mutation, and she initiated osimertinib treatment." (PMID 33260805, 2020). "Activation of the EGFR signalling pathway in cancer cells has been linked with tumour growth, increased cell proliferation, angiogenesis, metastasis, and inhibition of apoptosis." (PMID 32632202, 2020). "CD68+ cells within the tumor niche exhibited more intensive infiltration in wild-type EGFR than in mutated tumors, and were related to lymph node invasion." (PMID 33194645, 2020). "ABT-414 (depatux-m), comprising ABT-806 conjugated to the cytotoxic monomethyl auristatin F (MMAF), has demonstrated single-agent activities across several tumor types in which EGFR is amplified, mutated (e.g., EGFRvIII mutations) or over-expressed." (PMID 33256808, 2020). "For example, both tumor samples and PDOs harbored driver mutations in four patients (EGFR L858R, n = 2; EGFR Ex20 ins, n = 1; and KRAS G12C, n = 1)." (PMID 32633046, 2020).
tumor (continued). "By comparing EGFR mutations status from plasma (MassARRAY) with matched tumor tissues, an overall concordance of EGFR mutational status of 86.4% (38/44) was observed." (PMID 33105541, 2020). "EGFR mutations were associated with women, non‐smokers, normal level of serum tumor markers, and adenocarcinoma (P < 0.001)." (PMID 32729257, 2020). "The molecular tumor status of the choroidal metastasis patients was consistent with that of the remaining population, as 85% had a common activating EGFR mutation." (PMID 33272243, 2020). "In a single-arm phase II study, trastuzumab-paclitaxel showed anti-tumor activity with an ORR of 46% (11/24) of EGFR TKI pretreated patients with an activating EGFR mutation and HER2 mutation." (PMID 32448366, 2020). "Several European EQA programs have reported on the performance of predicitive testing for both activating and resistant clinically relevant EGFR mutations in tumor tissue samples for individual laboratories and different technologies." (PMID 32357863, 2020). "This variant results from a deletion and a mutation in the exon of EGFR, which create a tumor-specific and immunogenic neoantigen." (PMID 32194541, 2020). "In CMT high EGFR expression has been associated with increased angiogenesis, large tumor size, tumor necrosis, higher mitotic rates, advanced clinical stage and malignancy." (PMID 32411603, 2020). "Tumor tissue biopsy is the standard method for EGFR mutation detection but is invasive, is resource-intensive, and has risks of complications." (PMID 32599934, 2020). "Collectively, these results indicate that high tumor expression levels of both EGFR and BIRC5 are associated with more rapid development of liver and lung metastases in patients compared to tumors with low expression of one or both of these genes." (PMID 32001757, 2020). "ASK120067 exhibited potent anti-proliferation activity in tumor cells harboring EGFR T790M and sensitizing mutations (PC-9 and HCC827) while showed moderate or weak inhibition in cells expressing EGFR WT." (PMID 32404161, 2020). "The tumor from the patient contains drug-sensitive EGFR mutations in addition to documented T790M mutations (according to local testing results)." (PMID 32404161, 2020). "WES analysis of the recurrent tumor showed a loss of tumor cells harboring the activating EGFR A289V mutation, most likely due to the targeted anti-EGFR therapy." (PMID 31376079, 2020). "Patients were asked for participation and signed consent forms before collecting samples for EGFR mutation analysis (5 mL of peripheral blood and matched tumor tissues after confirming histology assessments)." (PMID 32746896, 2020). "Lumbar puncture and MRI of brain and spine revealed LM and targeted NGS sequencing from the CSF identified an activating EGFR mutation (Exon 21) (see also #1), which was later confirmed in the primary tumor biopsy by PCR as well." (PMID 31903155, 2020). "Occasionally, complex mutations occur, meaning a single tumor sample has two or more different EGFR mutations." (PMID 33363040, 2020). "GBM cells frequently harbor Epidermal Growth Factor Receptor amplification (EGFRwt) and/or activating mutation (EGFRvIII), generating at least two different cellular subpopulations within the tumor." (PMID 32024816, 2020). "Circulating-free tumour DNA from plasma/serum samples of NSCLC patients was found to correlate with EGFR mutation with high concordance rate (94.3%) and specificity (99.8%)." (PMID 33198090, 2020). "In mediation analysis to identify causal associations between the tumor location and survival, EGFR mutations showed a statistically significant indirect effect (P = 0.005)." (PMID 32913267, 2020). "EGFR mutation status of CSF-ctDNA was concordant with the EGFR mutation status of primary tumor in 88.9% (16/18) of patients." (PMID 32650387, 2020). "In this study, the two EGFR mutation tests were concordant in more than 90% of tumor and plasma samples." (PMID 32224854, 2020).
tumor (continued). "The most common EGFR variant, EGFRvIII (de2-7 EGFR) promoted tumor cell growth and inhibited cell sensitivity to 5-FU." (PMID 32549224, 2020). "The predictive model of nomogram built by these factors (smoking, pathology, location, EGFR mutation status, age, tumor diameter, clinical N stage, consolidation chemotherapy and radiation dose) shows a potential predictive value in clinical practice." (PMID 32070383, 2020). "This rich source of tumor DNA can be used to quickly detect driver and resistance EGFR mutations using digital droplet PCR (ddPCR), with high concordance between supernatant and cell pellet." (PMID 33207539, 2020). "These specimens were selected for their preserved condition, tumour area and well-clarified pathological diagnosis and EGFR mutation status (L858R mutation, nine specimens; Ex19del mutation, nine specimens; no Ex19del or L858R mutation, 18 specimens)." (PMID 32616892, 2020). "Here the MassARRAY based technology showed an overall concordance rate of 86.4% between the EGFR mutational status in tumor tissue vs. liquid biopsy." (PMID 33105541, 2020). "Increased investigation into the factors affecting recurrence, particularly tumor molecular genetics such as EGFR mutations, is needed." (PMID 32523650, 2020). "Here we provide compelling evidence for improved variant calling (potentially including detection of actionable EGFR mutations in PFPE Tumour FNA preparations) by the use of PAXgene® fixation that were absent in FFPE comparators." (PMID 31571426, 2020). "Previous studies using radiolabeled [11C] erlotinib, a first-generation reversible EGFR TKI showed that uptake of [11C] erlotinib was significantly higher in tumours with an EGFR mutation." (PMID 32804306, 2020). "With the trait of cobas, these samples with limited tumour cellularity potentially cause EGFR mutation detection failure." (PMID 32028905, 2020). "Although tumor EGFR expression is associated with fluorescence intensity, only low levels of EGFR expression are required for imaging." (PMID 32942549, 2020). "To understand the molecular traits underlying these different anti-tumor effects, we evaluated the expression of wild-type EGFR and EGFRvIII, two notable alterations frequently detected in GBMs." (PMID 33142709, 2020). "Although the presence of the EGFR T790M mutation seems to be sufficient to induce tumour formation in mouse models, this mutation is characterised as weakly oncogenic." (PMID 32104210, 2020). "Tumor analysis for EGFR mutations is therefore routine in clinical practice to predict response to therapy in lung adenocarcinoma." (PMID 32012988, 2020). "The abnormal proliferation of tumour cells is one reason for tumour heterogeneity, and this situation resulted in different λHU values in the VP of the lesions between different EGFR mutation statuses." (PMID 32103127, 2020). "Decreased p120ctn has been identified as such a biomarker, and we have shown here that decreased p120ctn can indeed cause a tumor to be resistant to EGFR-targeted therapies." (PMID 33112928, 2020). "The air bronchograms showed that certain tumours had not yet invaded the bronchus, suggesting a weak aggressiveness of tumours with EGFR mutation." (PMID 32690092, 2020). "Since then, a few case reports have confirmed the ability of first- or second-generation TKIs to induce choroidal metastasis regression in patients with tumor EGFR mutation." (PMID 33272243, 2020). "HB-EGF is part of the EGF family and can bind to EGFR and ErbB4, which have been associated with malignant transformation in several human tumours." (PMID 32386517, 2020). "As new-generation EGFR-TKIs (e.g. osimertinib) 6, 7 have been developed recently for patients who showed resistance to conventional EGFR-TKIs, frequent examination of the tumor susceptibility to EGFR-TKIs became very important." (PMID 32373206, 2020).